HSF1 (heat shock transcription factor 1)
Diseases named in the same sentence as HSF1 in open-access papers (continued):
Sharing a sentence is not in itself a finding about the gene and the disease.
tumor (continued). "We also investigated the role of HSF1 in vivo and found that the tumor volumes and weights were further reduced in HSF1‐knockdown mice compared with the scrambled control mice after cotreatment with erastin and celastrol." (PMID 33675143, 2021). "Until now, pericentric heterochromatin of chromosome 9 has been identified as the primary target of HSF1, in both normal and tumor heat-shocked cells." (PMID 33547955, 2021). "Through double IF staining, we showed that HSF1 was primarily expressed in tumor cells and located in the nuclei of GBC cells, while abundant α-SMA+ CAFs surrounded HSF1+ GBC cells." (PMID 33407730, 2021). "Specially, HSF1 is found to play an important role in multiple cancers, which promotes cell invasion, migration, and proliferation of tumor cells." (PMID 34107992, 2021). "HSF1 activity is augmented in many tumor contexts in a way that resembles a chronic state of stress, characterized by high levels of HSP gene expression." (PMID 34845419, 2021). "Beyond its involvement in carcinogenesis in mice, it has been shown that inhibition of HSF1 significantly reduces tumor proliferation and survival." (PMID 33808130, 2021). "It is also involved in the inhibition of apoptosis and drug resistance, whereas HSF1 regulates tumor progression during the metastatic process and is used as a biomarker for tumors that are progressing toward metastasis." (PMID 34845419, 2021). "Tumorigenesis in several animal models was shown to be HSF1 dependent, and HSF1 knockout significantly decreased tumor formation and progression." (PMID 34203709, 2021). "HSF1 transcriptional activity is closely related to protein translation, and thus, it mediates protein synthesis and induces remodeling to support the tumor state." (PMID 34064083, 2021). "Activated HSF-1 translocates to the nucleus to promote the transcription of HSPs during oncogenesis, facilitating rapid tumor cell proliferation." (PMID 34775489, 2021). "We observed that HSF1 overexpression remarkably increased the number of infiltrating α-SMA+ CAFs in tumor microenvironment, which was confirmed by IHC and western blot analyses using an anti-mouse α-SMA antibody." (PMID 33407730, 2021). "One such inhibitor, CL-43, was found to reduce the activity of the HSF1 master transcription factor and to decrease the content of heat shock proteins in a variety of tumor cell types, and we confirmed these effects in DLD1 cells." (PMID 34199046, 2021). "In contrast, it is suggested that HSF1 supports and contributes to tumour growth, proliferation and metastasis." (PMID 34439354, 2021). "Reduced TUNEL staining and reduced tumor-free survival was reported in Hsf1+/+ Neu+ experimental tumors compared to Hsf1+/− Neu+, indicating higher rates of apoptosis in Hsf1+/− tumors." (PMID 32331382, 2020). "Despite some discrepancy (HSP27 vs. HSP40), HSF1 activation and subsequent expression of inducible chaperones (HSPs) in tumor cells clearly promote the CSC phenotype’s acquisition." (PMID 32268506, 2020). "First, metformin (chemical activator of AMPK, metabolic stressor and popular anti-diabetic drug) was found to induce AMPK-dependent phosphorylation of HSF1 at Ser121, which inactivated the factor and provoked proteotoxic stress in tumor cells." (PMID 32456366, 2020). "Hsf1 was also shown to be an important factor for the emergence of an EMT phenotype in experimental tumor cells driven by the Neu oncogene or TGF-β treatment, as well as through control of the EMT regulator Slug downstream of HRG and HER2." (PMID 32331382, 2020). "With roles in both angiogenesis and the Warburg effect, HSF1 therefore appears to exert a major influence on the bioenergetics of tumor cells." (PMID 32331382, 2020). "Our analyses further demonstrate HSF1 mRNA levels to be frequently increased in human tumor tissue relative to normal tissues." (PMID 32331382, 2020).
tumor (continued). "Secretion of CXCL12/SDF1 and TGF-β by CAFs promotes tumorigenesis, and TGF-β increases HSF1 levels in tumor cells." (PMID 32331382, 2020). "HSF1 signaling in fibroblasts activates a specific tumor-supporting transcriptional program via upregulation of TGF-β and CXCL12, which act both in autocrine and paracrine manner." (PMID 33096815, 2020). "It has been shown that downregulation of heat shock transcription factor 1 (HSF1) inhibits tumor growth and promotes cellular senescence by regulating HSP70." (PMID 32121660, 2020). "Two studies stand out that demonstrated the importance of the HSF1-mediated transcriptional programs specific for malignant transformation and tumor progression." (PMID 32408596, 2020). "There is also strong evidence to indicate the HSF1/heat shock system has an important role in modulating the transcriptional responses stimulated by the stromal–tumor interplay." (PMID 31514477, 2019). "HSF-1 is a ubiquitously expressed transcription factor that plays a central role in tumor biology (e.g., malignant transformation, carcinogenesis, and metastasis)." (PMID 31569342, 2019). "In order to inhibit HSF1 in tumor cells with an extremely high HSP70 content, like glioblastoma, the protein kinase inhibitor D11 was applied together with 17-AAG, which is known to suppress the HSP90 activity." (PMID 31652993, 2019). "For example, HSF1 was shown to regulate transcription within tumor cells upon co-culture with fibroblasts, and within fibroblasts upon co-culture with tumor cells." (PMID 31514477, 2019). "The connection of metabolic and proteotoxic stress was demonstrated in experiments showing that an activation of AMPK by metformin which suppresses the HSF1 activity by phosphorylation of Ser121 inhibited tumor cell growth." (PMID 31652993, 2019). "Compared to normal cells, most human tumor cells exhibit an upregulated expression of HSF-1 and HSPs already under physiological conditions due to an overexpression of oncogenic proteins that require HSPs for its proper folding." (PMID 31569342, 2019). "In CAFs, HSF1 promotes tumour growth by inducing the production of secreted factors such as TGFβ and SDF16." (PMID 30631061, 2019). "Since most Hsp90 inhibitors activate HSF-1 that induces the transcription of cytoprotective and tumor-promoting stress proteins such as Hsp70 and Hsp27, a combined approach consisting of HSF-1 knockdown (k.d.)and Hsp90 inhibition was investigated." (PMID 31569342, 2019). "HSF-1 activates the heat shock response in normal and tumor cells following stress, and thereby induces the synthesis of Hsp70 and Hsp27." (PMID 31569342, 2019). "On the other hand, Hsf1 also exerts a pro-oncogenic function through its ability to promote proteostasis in rapidly growing tumor cells." (PMID 31124783, 2019). "Taken together, our results show that high HSF1 expression is significantly correlated with advanced tumour progression and poor prognosis." (PMID 30326922, 2018). "HSF1 knockout mice are remarkably resistant to tumor induction by oncogenes through e.g., modulating the expression of a broad set of genes involved in cell-cycle regulation, signaling, metabolism, adhesion, and protein translation." (PMID 29875343, 2018). "The transcription factor, heat shock factor 1 (HSF1), influences the expression of heat shock proteins as well as other activities like the induction of tumor suppressor genes, signal transduction pathway, and glucose metabolism." (PMID 29494616, 2018). "In this study, we have found that high expression of HSF1 in GC tissues is related to more advanced depth of invasion, lymph node metastasis, distant metastasis and tumour-node-metastasis stage." (PMID 30326922, 2018).
tumor (continued). "Conversely, CBL0137 can downregulate HSF1 to inhibit heat shock responses brought by hyperthermia, thereby increasing tumor cell apoptosis." (PMID 30581774, 2018). "Like molecular chaperones, HSF1 promotes the survival of tumor cells and fosters the growth of tumor cells in culture." (PMID 29930764, 2018). "HSF1 also plays a vital role in tumor biology e.g. by promoting proliferation and survival upon oncogenic stimuli." (PMID 30131848, 2018). "It was found that HSF1 was strongly upregulated at mRNA and protein level in c-Myc-positive tumor samples." (PMID 30261904, 2018). "MiR-644a expression was inversely correlated with heat shock factor 1 (HSF1) expression, tumour diameter and TNM stage." (PMID 29898735, 2018). "HSF1 is upregulated in GC tissues compared with non-tumour tissues in the TCGA cohort and FAHSYSU cohort." (PMID 30326922, 2018). "This revealed high expression of HSF1 mRNA in tumor samples across all datasets when compared to matched normal samples." (PMID 30131848, 2018). "A protective role of quercetin in tumor ablation was highlighted with a mechanism involving HSP70 with HSF1 pathway in thermal ablation of solid tumors." (PMID 30356024, 2018). "Representative images from the seminal vesicles and metastatic sites showed HSF1 expression in infiltrating tumor cells." (PMID 30131848, 2018). "Subsequently, we observed low expression of HSF1 in the miR-644a mimic group tumours by IHC and western blotting." (PMID 29898735, 2018). "A growing number of studies have demonstrated that HSF1 is overexpressed in a series of solid tumors, and elevation of HSF1 expression is correlated with poor survival of tumor patients." (PMID 30261904, 2018). "The aim of this study was to search for a safer HSF1 inhibitor that would be able to sensitize tumor cells to traditional anticancer drugs and thus to reduce the dose of chemotherapeutic medicine." (PMID 29930764, 2018). "The role of activation of NRF2 and HSF1 during the process of carcinogenesis is context dependent, and both tumor prevention as well as tumor promotion effects have been described." (PMID 28887499, 2017). "Heat shock transcription factor-1 (HSF-1) guards the cancerous cells proteome against the alterations in protein homeostasis generated by their hostile tumor microenvironment." (PMID 29348836, 2017). "HSF1 promotes tumor initiation and progression, and supports proliferation of malignant tumor cells." (PMID 29158484, 2017). "HSF1 has been shown to play a role in several aspects of tumor progression including tumorigenesis, metabolism, epithelial-to-mesenchymal transition (EMT), and metastasis." (PMID 29088759, 2017). "Blockade of the PI3K/Akt/mTOR signalling axis was shown to attenuate the Heat Shock Factor (HSF1)-driven cellular heat shock stress response (HSR) in tumor cells." (PMID 28794469, 2017). "Unconstrained activation of the HSF1 transcription factor has been detected in multiple tumor types, where it exerts pro-growth and survival functions." (PMID 28903330, 2017). "Recently, we and others have found that the heat shock factor 1 (HSF1) is necessary for sustaining the activity of the mTOR pathway or vice versa in mouse and human hepatocarcinogenesis as well as in many other tumor types." (PMID 29207593, 2017). "HSF1 itself is observed to be overexpressed in across different tumor types and to promote proliferation, migration, and invasion." (PMID 29268782, 2017). "We next asked if the ranks of HSF1-CanSig 8q genes in different primary tumor sites share similar patterns." (PMID 29268782, 2017). "Using an orthotopic xenograft mouse model, we found that combined targeting of AKT and HSF1 to significantly reduce tumor growth, induce tumor apoptosis, delay time to metastasis, and prolong host survival." (PMID 29088759, 2017). "Collectively, these data suggest that HSF1 inhibition decreased the tumor burden and abdominal invasion." (PMID 28783244, 2017).
tumor (continued). "To investigate the possible crosstalk between c-Myc and HSF1 pathways in hepatocarcinogenesis, we evaluated the status of HSF1 in c-Myc mouse tumor tissues." (PMID 29207593, 2017). "Consistently, we found that ErbB2 inhibition by lapatinib not only strongly suppressed tumor progression in ErbB2 mice, but does so, at least in part, via inactivation of HSF1." (PMID 27791982, 2017). "In this regard, several HSF1 blockers have been developed and showed remarkable anti-tumor activity in numerous preclinical models." (PMID 28903330, 2017). "The ranks of 20 out of 27 primary tumor sites are asymmetrically skewed to high ranks with statistical significance, suggesting the overexpression of HSF1-CanSig 8q genes is coordinated in those tumor sites." (PMID 29268782, 2017). "In contrast, our multivariable analysis that included age, tumor grade ER status, and treatment type confirmed that high HSF1 is an independent factor of poor clinical outcome in ER-positive breast cancer." (PMID 27713164, 2016). "ESCC patients with low HSF1 in both tumor cells and stromal cells had the longest survivals (P < 0.001)." (PMID 26511079, 2015). "Collectively, these observations suggest that inhibition of HSF1 in vivo decreases tumor burden and delays leukemogenesis." (PMID 26397138, 2015). "HSF1 is a tumor growth facilitator that enhances tumor glucose dependence via a heat-shock-independent transcriptional program." (PMID 26298773, 2015). "A number of studies have indicated that HSF1 plays a critical role in carcinogenesis, tumor progression and metastasis by regulating the expression of heat shock proteins and other molecular targets." (PMID 26511079, 2015). "HSF1 immunoreactivity was observed at various levels, and localization was observed in the nucleus and cytoplasm of both tumor cells and stromal cells." (PMID 26511079, 2015). "As shown by the luciferase assay, NZ28 inhibited not only the transcriptional activity of HSF1 but also that of NF-κB and Sp1 in H1339 and T47D tumor cells." (PMID 25854583, 2015). "Low levels of HSF1 activation both in stromal and tumor cells predict the best outcome for ESCC patients, suggesting that HSF1 activation is a potential biomarker for ESCC patient prognosis." (PMID 26511079, 2015). "High HSF1 expression in stromal cells was a better predictor for ESCC patients’ prognosis than its expression in tumor cells, especially in patients with metastatic ESCC." (PMID 26511079, 2015). "Our data reveal that the increasing expression of HSF1 is found in ESCC tumor cells and stromal cells reciprocally when they interplay with each other in the tumor microenvironment." (PMID 26511079, 2015). "The overexpression of HSF1 in the nucleus of tumor cells indirectly promotes tumorigenesis by enabling proliferation, invasion and metastasis." (PMID 26511079, 2015). "HLA-G transcription was found to be induced upon heat shock in tumor cell lines, by heat shock transcription factor 1 (HSF1) binding to a heat shock element (HSE) present in HLA-G but not in other HLA class I genes." (PMID 25870595, 2015). "In the current study, Pearson’s correlation coefficient and a linear regression analysis were applied to analyze the correlation between the expression levels of HSF1 in tumor cells and in stromal cells." (PMID 26511079, 2015). "HSF1 has been described to have an important role in carcinogenesis as shown by its role in tumour initiation and progression through the regulation of the expression of Hsps and other targets." (PMID 25708542, 2015). "As in tumor cells, a high expression level of HSF1 in stromal cells was also found in samples from 74 (55.2 %) of the 134 patients." (PMID 26511079, 2015). "Although mechanisms regulating the heat shock response in tumor cells are not fully understood, it is well established that heat shock response strongly depends on the transcriptional activity of HSF1." (PMID 25954247, 2015).
tumor (continued). "With respect to ionizing irradiation, a simultaneous treatment of tumor cells with the HSF1 inhibitor NZ28 and the Hsp90 inhibitor NVP-AUY922 has been shown to potentiate the radiosensitizing effect mediated by NVP-AUY922 alone (unpublished data)." (PMID 25854583, 2015). "HSF1 was present in the nucleus mainly in Eca109 tumor cells, and present in the nucleus or distributed between the cytoplasm and a diffuse nuclear localization in stromal fibroblasts." (PMID 26511079, 2015). "We previously established a link between PKCθ and HSF1, a transcription factor known to induce tumor glucose dependency, namely direct phosphorylation and heat-shock-independent activation of HSF1 by PKCθ." (PMID 26298773, 2015). "In Eca109 xenograft tumors, both tumor cells and stromal fibroblasts showed stronger expression of HSF1." (PMID 26511079, 2015). "The interaction of tumor cells and stromal fibroblasts increases the expression of HSF1 reciprocally in tumor microenvironment." (PMID 26511079, 2015). "HSF1 expression was not only found in the ESCC tumor cells but also in stromal cells, primarily close to tumor cells in the microenvironment of ESCC tissues." (PMID 26511079, 2015). "The tumor/normal (T/N) ratio of HSF1 message signals varied from approximately 1.0- to 15.6-fold in eight paired tissues." (PMID 26511079, 2015). "In that respect, blocking the NRF2, HIF1, and HSF1 pathways holds the highest potential to reduce the extent of tumor cell survival post-PDT." (PMID 26516076, 2015). "Both Eca109 tumor cells and the mice stromal fibroblasts showed strong HSF1 positivity in in vivo tumor xenografts." (PMID 26511079, 2015). "Based on the criteria described in the methods section, a high expression level of HSF1 in tumor cells was noted in samples from 74 (55.2 %) of the 134 patients." (PMID 26511079, 2015). "Of the 67 HCC patients, 14 out of 27 HCC patients who had intact tumor membranes were HSF1-positive (51.9%)." (PMID 25199534, 2014). "The biomarkers that represent HSF1 transcription activation in tumor tissues are currently being investigated." (PMID 25199534, 2014). "By contrast, 32 out of 40 (80.0%) HCC patients with broken tumor membranes were HSF1-positive and HSF1 expression levels were notably higher in membrane-broken HCC than those in membrane-intact tumors." (PMID 25199534, 2014). "Down-regulation of HSF1 expression by siRNA also had a great impact on the viability of tumor cells, but it was neutral for non-tumor cell lines." (PMID 24467529, 2014). "In these tumor models, HSF1 is involved in regulating tumor initiation, development and metastasis, and is considered a novel non-oncogenic oncogene." (PMID 25199534, 2014). "There is rapidly growing evidence that HSF1 supports tumor initiation and growth, as well as metastasis and angiogenesis." (PMID 24467529, 2014). "Development of these tumors is dependent on HSF1 and in Hsf1 knockout mice tumor-free survival is dramatically prolonged." (PMID 24467529, 2014). "It has been reported that HSF1 stimulates different cellular processes characteristic for tumor progression, including aneuploidy, anchorage-independent and mitogen-independent growth, cell migration, angiogenesis, chemoresistance, and autophagy." (PMID 24467529, 2014). "Insufficient angiogenesis in Hsf1-/- mice is associated with the suppression of the HIF1 pathway, which is involved in tumor angiogenesis." (PMID 24467529, 2014). "More importantly, the combination of HSF1 knockdown with HSP90 inhibition prevents tumor growth significantly in xenograft mouse model (stasis or regression)." (PMID 23615731, 2013). "Recent studies have shown that although HSPs expression is important for the tumor initiation, a network of genes regulated by HSF1 in malignant cells is distinct from the transcriptional program induced by heat shock." (PMID 24165036, 2013).